POU3F3 (POU class 3 homeobox 3)
Description:
Transcription factor that acts synergistically with SOX11 and SOX4. Plays a role in neuronal development. Is implicated in an enhancer activity at the embryonic met-mesencephalic junction; the enhancer element contains the octamer motif (5'-ATTTGCAT-3') (By similarity).
Synonyms: Brain-1; Oct-8; BRN1; OTF8; SNIBFIS
Tractability: PROTAC: ubiquitination databases record sites on it; its protein half-life has been measured.
Target class: Transcription factor
Gene: Protein-coding gene on chromosome 2 (104,853,287 to 104,858,574, forward strand). Ensembl gene ENSG00000198914.
Subcellular location: Nucleus
Subcellular location (Human Protein Atlas): Nucleoplasm
Pathways (Reactome):
Developmental Biology: Nephron development
Gene Ontology:
Molecular function: protein homodimerization activity; DNA-binding transcription factor activity; DNA-binding transcription factor activity, RNA polymerase II-specific; RNA polymerase II cis-regulatory region sequence-specific DNA binding; sequence-specific DNA binding; DNA binding; HMG box domain binding
Biological process: positive regulation of DNA-templated transcription; central nervous system development; metanephric ascending thin limb development; metanephric DCT cell differentiation; metanephric loop of Henle development; metanephric macula densa development; metanephric thick ascending limb development; negative regulation of apoptotic process; negative regulation of DNA-templated transcription; positive regulation of cell population proliferation; positive regulation of gene expression; regulation of transcription by RNA polymerase II; brain development; regulation of DNA-templated transcription
Cellular component: nucleoplasm; nucleus; chromatin; RNA polymerase II transcription regulator complex
Genetic constraint (gnomAD): Loss-of-function variants: 1 observed, 9.84 expected, observed/expected ratio (o/e) 0.1, 90% interval 0.035 to 0.48. That is too few expected variants to judge how well the gene tolerates losing a copy. Missense variants: 556 observed, 549.37 expected, observed/expected ratio (o/e) 1.01, 90% interval 0.94 to 1.09. Synonymous variants: 395 observed, 278.16 expected, observed/expected ratio (o/e) 1.42, 90% interval 1.31 to 1.54.
Gene-disease validity (ClinGen):
ClinGen rates the evidence that POU3F3 causes each of these diseases.
complex neurodevelopmental disorder (autosomal dominant): Definitive. A disorder that involves more than one phenotype associated with the central nervous system, including but not limited to intellectual disability, autism, and seizures (epilepsy).
Homologues: Orthologues: dog POU3F3 (99% identical), pig POU3F3 (99% identical), rat Pou3f3 (99% identical), mouse Pou3f3 (99% identical), chimpanzee POU3F3 (89% identical), rabbit POU3F3 (53% identical), Drosophila melanogaster acj6 (20% identical), Caenorhabditis elegans unc-86 (18% identical). Paralogues in human: POU3F2 (56% identical), POU3F4 (49% identical), POU3F1 (46% identical), POU2F1 (31% identical), POU2F2 (28% identical), POU2F3 (28% identical), POU5F1 (26% identical), POU5F1B (26% identical), POU1F1 (23% identical), POU4F2 (23% identical), POU6F2 (22% identical), POU4F3 (22% identical), and 5 more.
Diseases named in the same sentence as POU3F3 in open-access papers:
POU3F3 is named in the same sentence as 42 diseases in open-access papers, as found by Europe PMC text mining. Sharing a sentence is not in itself a finding about the gene and the disease. The quoted sentences say what the papers report.
esophageal squamous cell carcinoma (20 papers, 2015 to 2024). Esophageal squamous cell carcinoma (ESCC) is a type of esophageal carcinoma (EC) that can affect any part of the esophagus, but is usually located in the upper or middle third. "A recent study has shown that POU3F3 as a novel lncRNA is up-regulated in plasma of patients with esophageal squamous cell carcinoma, and the altered plasma lncRNA POU3F3 showed diagnostic potentials for this disease." (PMID 30602452, 2019). "Esophageal squamous cell carcinoma cells transfer POU3F3 to fibroblasts through exosomes, activating CAFs and promoting both tumor metastasis and resistance to cisplatin." (PMID 39717771, 2024). "The tumor promoting effects of lncRNA POU3F3 were reported in esophageal squamous cell carcinoma and cervical cancer." (PMID 33816296, 2021). "Previous studies discovered that lncRNA POU3F3 promoted the methylation of the POU3F3 gene for transcriptional repression in glioma and esophageal squamous cell carcinoma." (PMID 33816296, 2021). "Tong and co-workers discovered the role of exosomal lncRNA POU3F3 in esophageal squamous cell carcinoma (ESCC)." (PMID 33763348, 2021). "LncRNA POU3F3 (POU3F3) was first characterized as a potential oncogene in esophageal squamous-cell carcinomas." (PMID 35201451, 2021). "POU3F3 lncRNA was also shown to be transferred from esophageal squamous cell carcinoma cells to normal fibroblasts and mediate their activation." (PMID 33572359, 2021). "LncRNA POU3F3 (POU3F3) is overexpressed and plays oncogenic roles in esophageal squamous-cell carcinomas." (PMID 35201451, 2021). "Long noncoding RNA POU class 3 homeobox 3 (POU3F3) is upregulated in esophageal squamous-cell carcinomas." (PMID 32615948, 2020). "LncRNA POU3F3 is upregulated in esophageal squamous-cell carcinomas, indicating its involvement in cancer biology." (PMID 32615948, 2020). "Long noncoding RNA POU class 3 homeobox 3 (POU3F3) is upregulated in esophageal squamous-cell carcinomas, suggesting its involvement in this disease." (PMID 32615948, 2020). "Among 14 esophageal squamous cell carcinoma-related lncRNAs, lncRNA POU3F3 (lnc-POU3F3) in exosomes facilitates the reprogramming of normal fibroblasts to CAFs." (PMID 33050576, 2020). "It is known that lncRNA POU3F3 is up-regulated in plasma of patients with esophageal squamous cell carcinoma." (PMID 30602452, 2019). "Linc-POU3F3 is a lncRNA that is approximately 4-kb upstream from the transcription factor POU3F3 gene, which promotes cell viability and proliferation in esophageal squamous cell carcinoma cells." (PMID 29721215, 2018). "Linc-POU3F3 is up-regulation in esophageal squamous cell carcinoma samples and promotes tumor development." (PMID 29214011, 2017). "Considering the fact that POU3F3 is upregulated in esophageal squamous-cell carcinomas, POU3F3 may also participate in lung squamous cell carcinoma." (PMID 32615948, 2020). "Up-regulation of lncRNA POU3F3 has been observed in esophageal squamous cell carcinomas, indicating its oncogenic role, while its expression pattern and functionality in other human disease is unknown." (PMID 30602452, 2019). "Up-regulation of lncRNA POU3F3 has been observed in esophageal squamous cell carcinomas, while its expression pattern and functionality in other human disease is unknown." (PMID 30602452, 2019). "In addition, other potential plasma lncRNA markers have been identified, for instance, HULC for hepatocellular carcinoma, lncRNA-UCA1 for lung cancer, POU3F3 for esophageal squamous cell carcinoma." (PMID 27912775, 2016). "However, the functions of lncRNA POU3F3 in esophageal squamous cell carcinoma, as well as its involvement in other human diseases are unknown." (PMID 30602452, 2019). "In the present study, we identified a lincRNA as a novel biological marker in CRC, termed as linc-POU3F3, whose altered expression was previously documented in esophageal squamous cell carcinoma cells (ESCC) and glioma." (PMID 26510906, 2016).
esophageal squamous cell carcinoma (continued). "In esophageal squamous cell carcinoma, for example, the PDGFβ/PDGFRβ/FOXO1/DNM3OS signaling axis and the POU3F3/IL-6 pathway play significant roles." (PMID 39717771, 2024). "For example, lncRNA POU3F3 could serve as a potential biomarker for esophageal squamous cell carcinoma (ESCC) diagnosis, and the combination of POU3F3 and SCCA was more efficient for ESCC detection, in particular for early tumor screening." (PMID 26096073, 2015). "High levels of plasma exosomal lncRNA POU3F3 correlated significantly with lack of complete response to cisplatin and poor survival in esophageal squamous cell carcinoma patients." (PMID 33572359, 2021).
glioma (18 papers, 2015 to 2025). A benign or malignant brain and spinal cord tumor that arises from glial cells (astrocytes, oligodendrocytes, ependymal cells). "Other studies have highlighted the crucial roles of lncRNA colon cancer-associated transcript 2 (lncRNA-CCAT2) and lncRNA POU Class 3 Homeobox 3 (lncRNA-POU3F3) in glioma-associated angiogenesis." (PMID 40764607, 2025). "Moreover, R-loops in Pou3f3/Brain-1 extended into the neighboring Pantr1 (Pou3f3 adjacent non-coding transcript 1) gene, which encodes a long non-coding RNA implicated in glioma development." (PMID 35927309, 2022). "Second, the levels of lnc-POU3F3 were upregulated in glioma tissue and significantly correlated with the advanced tumor stage." (PMID 36438184, 2022). "In this context, it is interesting to note that the overexpression of Linc-POU3F3, a non-coding RNA that suppresses the expression of POU3F3 mRNA, promotes cell viability and proliferation of glioma cells." (PMID 32999376, 2020). "As an example, glioma cells release exosomes loaded with lncRNA-POU Class 3 Homeobox 3 (POU3F3), which are in turn internalized with endothelial cells." (PMID 32992718, 2020). "In cancer types such as colorectal cancer and glioma, lncRNA POU3F3 was overexpressed in tumor tissues and positively correlated with tumor grade." (PMID 32637576, 2020). "It is thought provoking, however, that another lncRNA known as POU class 3 homeobox 3 (POU3F3) overexpressed in glioma cells is also sorted into exosome-like EVs and plays a documented role in angiogenic responses." (PMID 30585246, 2018). "The expressions of H19, MALAT1 and POU3F3, for instance, were positively correlated with more malignant glioma phenotypes, and H19 also modulates glioma cell invasion." (PMID 26230711, 2015). "The oncogenic role of lncRNA POU3F3 was verified in glioma and triple-negative breast cancer." (PMID 33816296, 2021). "Moreover, the elevated lncRNA POU3F3 expression was also reported in glioma, esophageal cancer, and cervical cancer, which was correlated with cell proliferation, migration, and invasion." (PMID 33816296, 2021). "Additional lncRNAs that are implicated in glioma cell growth include XIST and POU3F3." (PMID 28423669, 2017). "POU3F3 promotes cell viability and proliferation in glioma cells." (PMID 26252651, 2015). "Similarly, the POU class 3 homeobox 3 (POU3F3) was upregulated in glioma tissue." (PMID 38392967, 2024). "For instance, it has been demonstrated that glioma cells might stimulate angiogenesis by transferring linc-CCAT2 and linc-POU3F3 to endothelial cells through exosomes." (PMID 35448031, 2022). "There are several other lncRNAs that impact glioma or GSC biology, such as XIST and linc‐POU3F3." (PMID 30117678, 2018).
melanoma (6 papers, 2021 to 2025). A malignant, usually aggressive tumor composed of atypical, neoplastic melanocytes. "Overexpression of POU3F3 is associated with increased melanoma cell proliferation, whereas overexpression of MEG3 induces the opposite effect." (PMID 41463281, 2025). "Further clinical studies supported that lncRNA POU3F3 was a risk factor for the disease progression of melanoma." (PMID 33816296, 2021). "A recent study examined the association between the lncRNA POU3F3 and MEG3 in tissue samples from 60 patients with melanoma." (PMID 41463281, 2025). "For instance, lncRNAs PSMG3-AS1 and MEG3 negatively regulate each other, affecting proliferation in endometrial carcinoma cells, while POU3F3 promotes melanoma cell proliferation by suppressing MEG3." (PMID 40350996, 2025). "miR-650 also contributes to drug resistance, such as by upregulating dacarbazine (DTIC) resistance in melanoma through the lncRNA POU3F3/miR-650/MGMT (methylguanine-DNA-methyltransferase) axis, which turns miR-650 into a potential target for cancer treatment." (PMID 35331235, 2022). "Further studies also supported high lncRNA POU3F3 levels in the disease progression of patients with melanoma who received the DTIC-based chemotherapy." (PMID 33816296, 2021). "Our study suggested that the lncRNA POU3F3/miR-650/MGMT pathway is a novel target for improving the therapeutic efficiency of alkylating agents-based chemotherapy for melanoma." (PMID 33816296, 2021). "Our results supported that lncRNA POU3F3 was a detrimental factor for the disease progression of melanoma." (PMID 33816296, 2021). "Cox-regression and survival analysis indicated that the expression of lncRNA POU3F3 was a detrimental factor for the progression of melanoma." (PMID 33816296, 2021). "In the present study, we proved that POU3F3 plays a role as the upstream inhibitor of MEG3 in regulating melanoma cell proliferation." (PMID 35201451, 2021). "Our results indicated that lncRNA POU3F3 was a valuable biomarker for the disease progression of melanoma." (PMID 33816296, 2021). "Earlier, we screened out increased levels of lncRNA POU3F3 (also LINC01158) in DTIC-resistant melanoma cells, indicating a promising role of lncRNA POU3F3 in the acquired DTIC resistance." (PMID 33816296, 2021). "The cell viability analysis indicated that the expression of lncRNA POU3F3 maintained the survival of melanoma cells with DTIC treatment." (PMID 33816296, 2021). "Tumor and adjacent healthy tissues collected from 60 melanoma patients were subjected to RNA extractions and RT-qPCRs to analyze the differential expression of POU3F3 and MEG2 in melanoma." (PMID 35201451, 2021). "Additionally, the lncRNA-POU3F3 expression level was elevated in dacarbazine-resistant melanoma cells, and knockdown of POU3F3 restored the sensitivity of cells to dacarbazine by secreting miR-650 and upregulating the expression of MGMT protein." (PMID 36601121, 2022). "In addition, the lncRNA POU3F3/miR-650/MGMT pathway has been revealed to function critically in DTIC resistance in melanoma." (PMID 35331235, 2022). "Our study explored the mechanism of lncRNA POU3F3-induced DTIC resistance in melanoma." (PMID 33816296, 2021). "In addition, a decreased miR-650 level was observed in lncRNA POU3F3 overexpressed melanoma cells in the qRT-PCR assay." (PMID 33816296, 2021). "Then, we assessed the functional role of lncRNA POU3F3 in melanoma cells." (PMID 33816296, 2021). "Our study revealed the oncogenic function of POU3F3 in melanoma." (PMID 35201451, 2021). "Thus, we explored the biological role of lncRNA POU3F3 in regulating DTIC-resistant melanoma cells, as well as their clinical significance in patients with malignant melanoma." (PMID 33816296, 2021). "Moreover, the flow cytometry analysis indicated that the miR-650 mimic transfection increased cell apoptosis with DTIC treatment, which reversed the overexpression of lncRNA POU3F3 induced the DTIC resistance in melanoma cells." (PMID 33816296, 2021).
melanoma (continued). "The results supported that lncRNA POU3F3 participated in the DTIC resistance of melanoma cells." (PMID 33816296, 2021). "Given that the limited survival time was calculated for patients in the late stage of melanoma and the increasing trends of the incidence, further clinical trials for an lncRNA POU3F3-targeted therapy is considered as a promising strategy for melanoma treatment." (PMID 33816296, 2021). "Our study identified an increased lncRNA POU3F3 level in DTIC-resistant melanoma cells." (PMID 33816296, 2021). "In addition, POU3F3 level in tumors increased with melanoma progressing from stage I to IV (p < 0.05)." (PMID 35201451, 2021). "In conclusion, POU3F3 is upregulated in melanoma and POU3F3 overexpression may promote melanoma cell proliferation by downregulating MEG3." (PMID 35201451, 2021). "In melanoma cells, POU3F3 and MEG2 were overexpressed to study the interactions between them." (PMID 35201451, 2021). "POU3F3 may promote melanoma cell proliferation by downregulating MEG3." (PMID 35201451, 2021). "In terms of the mechanism, lncRNA POU3F3 works as a competitive RNA to combine with miR-650; therefore, MGMT expression rises to a higher extent in melanoma cells." (PMID 35331235, 2022). "POU3F3 overexpression increased melanoma cell proliferation, while MEG3 overexpression decreased melanoma cell proliferation." (PMID 35201451, 2021). "In this study, a positive correlation was observed between lncRNA POU3F3 and the MGMT expression in DTIC-resistant melanoma cells in vivo and in vitro." (PMID 33816296, 2021). "CCK-8 assays were performed to analyze the roles of POU3F3 and MEG2 in regulating melanoma cell proliferation." (PMID 35201451, 2021). "Our preliminary deep sequencing analysis revealed the inverse correlation between POU3F3 and MEG2 across melanoma tissues, indicating the interaction between them in melanoma." (PMID 35201451, 2021). "We further accessed the correlation of lncRNA POU3F3 and MGMT in the DTIC resistance of melanoma cells." (PMID 33816296, 2021). "Molecular analysis indicated that lncRNA POU3F3 worked as a competitive endogenous RNA to regulate the levels of miR-650, and the lncRNA POU3F3/miR-650 axis determined the transcription of MGMT in melanoma cells to a greater extent." (PMID 33816296, 2021). "POU3F3 and MEG3 were overexpressed in A375 and M21 cells, two human melanoma cell lines, to further investigate their interactions in melanoma." (PMID 35201451, 2021). "Analysis of CCK-8 assay data showed that POU3F3 overexpression increased melanoma cell proliferation, while MEG3 overexpression decreased melanoma cell proliferation (p < 0.05)." (PMID 35201451, 2021). "In this study, we proved that POU3F3 promoted melanoma cell proliferation possibly by downregulating MEG3, a tumor suppressor in melanoma." (PMID 35201451, 2021). "In vitro experiments showed that POU3F3 overexpression decreased MEG3 expression in melanoma cells, while MEG3 overexpression failed to affect POU3F3." (PMID 35201451, 2021). "In the present study, we reported that POU3F3 overexpression only significantly affected the proliferation but not the migration and invasion of melanoma, indicating the specific involvement of POU3F3 in the regulation of melanoma growth." (PMID 35201451, 2021). "In addition, the interaction between POU3F3 and MEG3 characterized in this study provided new insights into the pathogenesis of melanoma." (PMID 35201451, 2021). "We found that POU3F3 was upregulated, while lncRNA MEG3 was downregulated in melanoma." (PMID 35201451, 2021). "POU3F3 negatively influences MEG3 levels in melanoma cells, while overexpression of MEG3 does not affect POU3F3 levels, suggesting interactions between POU3F3 and other factors." (PMID 41463281, 2025). "In the present study, POU3F3 overexpression downregulated MEG3 but failed to significantly affect the migration and invasion of melanoma cells." (PMID 35201451, 2021).
melanoma (continued). "However, compared to C and NC groups, POU3F3 overexpression decreased MEG3 expression in melanoma cells (p < 0.05), while MEG3 overexpression failed to significantly affect POU3F3 (p < 0.05)." (PMID 35201451, 2021).
cervical cancer (4 papers, 2018 to 2023). A primary or metastatic malignant neoplasm involving the cervix. "The cervical cancer growth-promoting function of POU3F3 was validated by POU3F3 knockdown." (PMID 37190145, 2023). "LncRNA POU class 3 homeobox 3 (POU3F3), activated by transcriptional factor SP1, improves the proliferation of cervical cancer cells by sponging miR-127-5p." (PMID 37190145, 2023). "The POU class 3 homeobox 3 (POU3F3) lncRNA is an oncogene seen in various human cancers, such as cervical cancer, nasopharyngeal carcinoma, and breast cancer." (PMID 33980320, 2021).
colorectal cancer (4 papers, 2016 to 2023). A primary or metastatic malignant neoplasm that affects the colon or rectum. "Previous studies demonstrated that Linc-POU3F3 (PANTR1) could promote tumor cell invasion in hepatocellular carcinoma and colorectal cancer." (PMID 36861062, 2023).